KRAS (KRas proto-oncogene, GTPase)
Diseases named in the same sentence as KRAS in open-access papers (continued):
Sharing a sentence is not in itself a finding about the gene and the disease.
cancer (continued). "Following this, genetic testing as an effort to classify cancer patients between EGFR(+) and KRAS(+) before prescribing anti-EGFR mAbs have been emphasized worldwide." (PMID 30042874, 2018). "Studies showed that most galectins are involved in the development of various cancers and the processes they involved in are mainly tumor cell transformation through interacting with oncogenes such as HRAS and KRAS." (PMID 29854732, 2018). "Patients undergoing both KRAS and EGFR testing lived an average of 66 miles away from an NCI cancer center compared to 85 miles for those undergoing EGFR testing." (PMID 29554880, 2018). "We sought to directly target oncogenic KRAS using the CRISPR/Cas9 system, and consequently impair the growth of cancer cells." (PMID 30089886, 2018). "The same authors also demonstrated linkages between upregulation of the complement pathway and upregulation of KRAS and PTEN-regulated pathways, both frequently involved in oncogenesis and maintenance of the cancer phenotype in vitro." (PMID 29456620, 2018). "By using cell-survival assays with MIA PaCa-2 (KRasG12C), CFPAC-1 (KRasG12V), BxPC-3 (wild-type KRas), Capan-1 (KRasG12V), and SW1990 (KRasG12T), we show that Spiclomazine treatment markedly reduces cell survival in these mutant cancer cell lines." (PMID 29467941, 2018). "Briefly, we found 34 somatic alterations, including eight genes recorded in the cancer gene list, and confirmed recurrent NOTCH1 (SNVs 6/9, indels 1/9), KRAS (SNVs 1/9), NRAS (SNVs 2/9), FBXW7 (SNVs 2/9), and MTOR (SNVs 2/9) mutations (Table EV1)." (PMID 29880602, 2018). "Many cancer-related pathways including WNT, PI3K/Akt, KRAS, and PTEN pathways have been reported in canines." (PMID 30205506, 2018). "However, mutant KRas-driven cancers may gain dependencies through other pathways." (PMID 30514931, 2018). "It has also been shown that CD44 forms complexes with CD147 at the cell surface of cancer cell lines, which is indicative of the pivotal and complex role CD147 plays in KRas-driven tumors." (PMID 29899869, 2018). "KRAS, NRAS, and HRAS are the 3 members of the RAS family of GTPases that are the most prevalent oncogenes in cancer progression and have similar cellular functions." (PMID 29568360, 2018). "Cell type-specific Exo proteins are so far most comprehensively explored for cancer and cancer stem cells (CSC), such as MART1, EGFRVIII, multidrug resistance gene 1, EpCAM, MET, mutant KRAS, and tissue factor." (PMID 29456536, 2018). "Target gene candidates in cancer therapy are mainly involved in oncogenes, angiogenesis and proliferation, like PLK1, EphA2, RRM2, KRAS, PKN3 and VEGF, which have been tested as target genes in early-phase clinical trials for RNAi-based cancer therapies." (PMID 30065155, 2018). "These GScores underline the biological relevance and clinical utility of both KRAS and EGFR genomic alterations in cancer." (PMID 29848362, 2018). "This leads to cancer transformation of RHEB Y35N stably expressing cell lines, similar to KRAS G12 V expressing cell lines." (PMID 29320991, 2018).
cancer (continued). "Considering that FAT1 is overexpressed in both KRAS+ and KRAS− CRCs, these data support the development of anti-CRC cancer vaccines in which the D8-FAT1 epitope is used in combination with other CRC-specific antigens, including mutation-derived neoepitopes." (PMID 30416985, 2018). "It is known that in cancer cells, NRAS and KRAS are often hyperactivated in comparison with HRAS and therefore NRAS and KRAS are much more important therapeutic targets in cancer when compared to HRAS14,15." (PMID 29891945, 2018). "With the caveat that the cell lines tested were derived from different cancers, PIP5K1A mediates growth driven by endogenous oncogenic KRAS in what appears to be an isoform-specific fashion." (PMID 30194290, 2018). "A meta-analysis was attempted to find out the efficacy of cancer therapy between PFS and OS patients in WT and MT KRAS." (PMID 29484148, 2018). "Compared to KRAS-GTP interaction, the relatively poor binding affinity of these compounds prompted a widely held perception that oncogenic KRAS was an “undruggable” cancer target." (PMID 28443025, 2017). "The obtained prediction of antipodal effects of KRAS and MYC induction on the drug sensitivity of cancer cells was then tested experimentally." (PMID 28152508, 2017). "The identification of KRAS mutations in pancreatic CTCs should be a sensitive tool to prove at least their pancreatic origin although these mutations can already be detected in intra-epithelial neoplasias of the pancreas (PanIn) and do not prove the presence of cancer." (PMID 29156783, 2017). "KRAS can also regulate other signaling pathways, such as PI3K-AKT, PLC-PKC, and RAL, which are also known to be involved in cancer progression." (PMID 28452926, 2017). "We also observed several mutations in the MAP kinase signaling pathway (14% of tumors), involving KRAS, NRAS, BRAF, and MAP2K1 oncogenes across multiple cancer types including hematologic, lung, ovarian, duodenal, biliary, and colorectal." (PMID 29100271, 2017). "While there are many members in this family, the most notable ones are HRAS, KRAS and NRAS because of their involvement in human cancers." (PMID 27965461, 2017). "Gene Sets Enrichment Analysis showed that GGT promotes cancer progression through EMT, KRAS, SRC and PKCA pathways." (PMID 28404903, 2017). "The model prediction of KRAS level being higher in the l-OS patient, together with the somatic mutation and with high ERK activation, could lead to the activation of the senescence program of the cancer cells as has been validated in human colon adenocarcinoma cancer models." (PMID 29137348, 2017). "However, its role in human KRAS-driven cancer remains unclear." (PMID 28220783, 2017). "KRAS belongs to the RAS family of proteins and is among the most frequently activated drivers of human cancers." (PMID 28640835, 2017). "To prospectively identify mechanisms through which HSP90-dependent cancer cells evade pharmacologic HSP90 blockade, we generated multiple mutant KRAS-driven cancer cell lines with acquired resistance to the purine-scaffold HSP90 inhibitor PU-H71." (PMID 28032595, 2017).
cancer (continued). "FGFR is also involved in autocrine activation of STAT3 as a positive feedback in many previously treated cancer cells that are driven by oncogenes such as EGFR, ALK, MET, and KRAS." (PMID 28030802, 2017). "We anticipated that effectively translating findings from studying cancer metabolism and its regulation by oncogenes like MYC or KRAS to the clinic will be accelerated through our understanding of how these oncogenes affect tissue specific metabolism in vivo." (PMID 28443280, 2017). "In this regard, KRAS and the PI3K/AKT/mTOR pathway are frequently dysregulated in cancer and, for such reason, are the most critical targets in clinical oncology." (PMID 27019364, 2016). "Hence, identification of differentially expressed proteins on the surface of cancer cells expressing oncogenic KRas may provide distinct opportunities for translation of these findings into innovative treatments aimed directly at proteins unique to or exceedingly upregulated on the KRas surface." (PMID 27894102, 2016). "Contrary to expectation, however, KRAS mutation status does not correlate with increased sensitivity to anti-mitotic agents when analysing a small in-house panel of cancer cell lines, three isogenic cell line pairs or a large database of anti-cancer drug responses." (PMID 27412232, 2016). "Immunohistochemistry was used to detect the differential expression of KRAS, BRAF and MLH1 in cancer tissues." (PMID 27323816, 2016). "In 1982-3, orthologs of viral ras oncogenes with point mutations were identified in transforming DNA fragments from human cancer cells both for HRAS and KRAS." (PMID 27102293, 2016). "The status of MLH1, BRAF and KRAS expression, as well as inflammation related TNF-α, COX-2, MMP-9, β-catenin and NF-κB of cancer tissues were assessed to calculate their correlation with different microbial phylotypes." (PMID 27323816, 2016). "With the exception of the relatively well-known KRAS, HRAS and NRAS proteins, little is known about how the interactions of the other RAS human paralogs affect cancer evolution and response to treatment." (PMID 27713118, 2016). "In the present report we show a significant relationship between oncogenic KRAS expression and enhanced levels of S100A10 in a panel of different human cancer cell lines." (PMID 27351226, 2016). "Derived from a completely different cancer, HCT116 harbors mutant G13D KRAS while its clonal derivative HKe3 contains wild-type KRAS36." (PMID 27892494, 2016). "Regions of high level gain or amplification encompassed key cancer genes such as MYCN (2p), the EVI1/MDS1 cluster (3q), FGFR1 (8p), OCT4 and MYC (8q) and KRAS (12p) of which a number are potential therapeutic targets." (PMID 26334103, 2015). "Whilst increased expression may promote senescence and reduce tumourigenesis, our data suggest that the preponderance of KRAS mutations in human cancers is not due to an oncogenically optimal low relative endogenous expression level of KRAS versus the other Ras isoforms." (PMID 26560143, 2015).
cancer (continued). "To address the functional relevance of miRNAs in mutant KRAS cancers, we transfected exogenous KRASG12V into human embryonic kidney 293 and MRC5 cells with wild-type KRAS and BRAF genes, and we comprehensively profiled the dysregulated miRNAs." (PMID 25756961, 2015). "Screening for synthetic lethality has recently revealed that combined inhibition of MK2 and Chk1 synergistically induced mitotic catastrophe and cell death in KRAS- and BRAF-driven cancer cells." (PMID 26295265, 2015). "Furthermore, in cancer cell lines with mutations in both KRAS and PIK3CA, MEK inhibitor could not induce the cell cycle arrest due to the sustained cyclin D1 expression." (PMID 26121043, 2015). "We achieved robust raw CT values for both small and large RNAs, including RNAs important for cancer research such as BRAF and KRAS, as well as specific miRNAs like let-7a and miR-142-3p that have previously been reported to be specifically enriched in EVs." (PMID 26317354, 2015). "The gene KRAS was ranked 1st in the DEG list and had the most connections to the cancer-related pathways." (PMID 25126556, 2014). "KRAS, NRAS, HRAS, BRAF, PIK3CA, PIK3R1 and PTEN are key cancer-related genes in the RAS/RAF and PI3K/PTEN signaling pathways." (PMID 25120700, 2014). "In our results, the sample with mutant cancer genes APC and KRAS, yielded an inferred probability of 0.95 for the order APC→KRAS, which was consistent with previous studies." (PMID 24586626, 2014). "Our finding that ZNF304 levels are elevated in both KRAS-positive CRC cells and hESCs is consistent with studies reporting a variety of similarities between cancer cells and stem cells." (PMID 24623306, 2014). "The authors showed a close similarity between human and dog mammary tumours regarding the perturbation of many cancer-related gene sets and pathways, e.g.: PI3K/AKT, KRAS, WNT-beta catenin and MAPK, as well as a group of genes specific for cancer stem cells." (PMID 24722858, 2014). "Moreover, while the safety, feasibility and potential efficacy of reovirus as a cancer therapy are currently being evaluated in multiple phase I-III clinical trials, the underlying molecular mechanism of by which reovirus preferentially induces oncolysis in KRAS mutant cells is not well understood." (PMID 24798549, 2014). "We have previously demonstrated that downregulation of DCLK1 can upregulate critical miRNAs in both in vitro and in vivo cancer models and results in downregulation of c-MYC, KRAS, NOTCH1 and EMT-related transcription factors." (PMID 24040120, 2013). "The six subtypes were named according their main respective biological characteristic as follows: C1, “CINImmuneDown”; C2, “dMMR”; C3, “KRASm” (for “KRAS-mutant”); C4 “CSC” (for “cancer stem cell”); C5, “CINWntUp”; and C6, “CINnormL”." (PMID 23700391, 2013). "Similar findings for EREG high vs. low were seen when we examined complex cancer genotypes: a) KRAS+BRAF, both wild type vs. any mutant, b) KRAS+BRAF+PIK3CA+NRAS, all wild type vs. any mutant." (PMID 23374602, 2013).
cancer (continued). "Also, mutational analysis for KRAS and BRAF discloses some possible interactions between type I and type II pathway and could be useful in detection of small proportion of high-grade carcinomas arising through type I pathway, with possible diverse clinical behavior and specific therapy requirements." (PMID 23388101, 2013). "In cancer cells, the expression of constitutive active AKT, KRAS or the activation of the mTOR pathway has been associated with an increased Warburg effect and higher sensitivity to glucose deprivation." (PMID 22662165, 2012). "We show that miR-126 is able to directly target KRAS; re-expression has the potential as a therapeutic strategy against PDAC and other KRAS-driven cancers." (PMID 22384141, 2012). "Indeed, activating KRAS, BRAF and PIK3CA mutations are able to bypass EGFR pharmacological inhibition, thereby resulting in a constitutive activation of the mitogen-activated protein kinase and AKT pathways, known to play a central role in cancer onset and progression." (PMID 22911782, 2012). "In addition to the mutational status of KRAS, the epidermal growth factor receptor (EGFR) ligands amphiregulin (AREG) and epiregulin (EREG) might function as bona fide biomarkers of cetuximab (Ctx) sensitivity for most EGFR-driven carcinomas." (PMID 22491422, 2012). "We recently identified somatic activating mutations in genes associated with the AKT and MAPK signaling pathways, including PIK3CA, KRAS, HRAS, and NRAS, in BM from breast and other cancers." (PMID 22567347, 2011). "Cancer cells with disruption of both HIF-1α and HIF-2α or oncogenic KRAS showed decreased aerobic respiration and ATP production, with increased ROS generation." (PMID 21073737, 2010). "Altogether, these data show that the presence of oncogenic KRAS and both HIF-1α and HIF-2α in cancer cells lead to increased cardiolipin level and enhanced mitochondrial respiration efficiency." (PMID 21073737, 2010). "Retrospective analysis of pts treated with cetuximab or panitumumab at an Italian and a Swiss cancer center.Primary or secondary endpoints were not defined.PCR amplification with specific primers followed by automated sequencing by ABI PRISM 3730 was used to identify KRAS and BRAF sequence variants." (PMID 20972475, 2010). "Next to the important prediction of drug response for metastatic colorectal carcinomas, KRAS mutations may also be decisive for drug decision in NSCLC in regard to Erlotinib or Gefitinib, because these kinase inhibitors seem to be ineffective in carcinomas with KRAS mutation." (PMID 21197450, 2010). "However, HRAS mutations are rarely seen in human cancers (4%), and whether romidepsin also inhibits transformation caused by the Ras isoforms most commonly mutated in human cancers (KRAS and NRAS; 21 and 8%, respectively) has not yet been addressed." (PMID 19682393, 2009). "Pathway analysis of gene expression data revealed a great degree of similarity in the perturbation of many cancer-related pathways, including the 'PI3K/AKT', 'KRAS', 'PTEN', 'WNT-beta catenin' and 'MAPK cascade'." (PMID 19327144, 2009). "To determine the requirement of RAS in these RAS-mutant cancer lines for cellular proliferation, we studied these lines for growth following induction of shRNAs that target NRAS or KRAS." (PMID 19492075, 2009). "Known cancer genes included focal amplifications of MYC (8q24.21), KRAS (12p12.1) and AKT2 (19q13.2), and homozygous deletions of TGFBR2 (3p24.1) and CDKN2A (9p21.3)." (PMID 18535672, 2008). "Notably, in several cancer types, a subset of cancer tissues exhibited KRAS E4 PSI values greater than 0.5, suggesting that KRAS4A was more abundant than KRAS4B in certain cancer tissues." (PMID 41368203, 2026). "Metabolic alterations in cancer cells are crucially prompted by the oncogenes MYC and KRAS." (PMID 41328353, 2026).